MUC1 (mucin 1, cell surface associated)
Diseases named in the same sentence as MUC1 in open-access papers (continued):
Sharing a sentence is not in itself a finding about the gene and the disease.
breast carcinoma (continued). "The results showed that Pink1 knockdown intensely constrained CCCP-induced cell proliferation and mammospheres formation not only in MDA-MB-468 cells, but also in BT549 cells, indicating MUC1 facilitates breast cancer progression by promoting Pink1-dependent mitophagy." (PMID 36289190, 2022). "Overexpression and aberrant glycosylation of MUC1 were found in over 90% of breast cancer patients." (PMID 35935930, 2022). "A CAR specific for both HER2 and MUC1 for breast cancer showed that dual targeting can lead to the delivery of complementary signals that enhance T-cell proliferation, and dual-target CARs specific for HER2 and IL13Rα2 mitigate antigen escape in a xenograft glioma model." (PMID 34831068, 2021). "Thus, it is anticipated that the high expression of MUC1 on breast cancer would allow target-specific imaging and therapy using synthetic MUC1-derived peptides." (PMID 33738611, 2021). "Optical and electrochemical platform-based ensemble biosensors and nanosensors for detecting and quantifying MUC1 have also been developed with electrochemiluminescence sensors to detect MUC1 protein exocytosis in breast cancer cells and MUC1 protein in their derived exosomes." (PMID 34207342, 2021). "Monitoring of MUC1 levels is a useful indicator of breast cancer remission status." (PMID 34439139, 2021). "Therefore, MUC1 is recognized as a promising marker for theranostics of breast cancer and has been targeted for imaging agent development." (PMID 33986665, 2021). "MUC1-ST, a glycoform of the mucin MUC1 carrying the ST antigen found in breast cancer patient serum, through Siglec-9 engagement, triggers the differentiation of a unique tumor-associated macrophage (TAM) subtype that has been associated with poor prognosis in breast cancer." (PMID 34975914, 2021). "MUC1, a molecule aberrantly glycosylated and overexpressed in a variety of epithelial cancers, was one of the first TAAs to be tested in a clinical trial of therapeutic cancer vaccines in patients with metastatic colon, pancreatic, and breast cancer." (PMID 34681560, 2021). "MUC1 interacts with the DNA-binding domain of ERα directly and thereby stabilizes ERα by blocking proteasomal degradation, resulting in enhanced ERα response gene transcription and the proliferation of breast cancer cells." (PMID 34681277, 2021). "Core 1 O-glycans were extensively exhibited in MUC1-overexpressing breast cancer cells." (PMID 33836774, 2021). "It gives us a hint that if an antigen specifically overexpressed in certain cancer, such as HER2 in breast cancer and MUC1 in lung cancer, the epitopes could be presented and effectively induce human T cells immunogenicity." (PMID 33469123, 2021). "Moreover, Siglec-9 has also been reported in myeloid cell-mediated cancer progression via binding to MUC-1 with sialylated T-antigen (MUC-1 ST) in breast cancer and pancreatic ductal adenocarcinoma to modulate tumor-associated macrophage differentiation." (PMID 34827170, 2021). "Li and colleagues detected MUC-1 positive human breast carcinoma MCF-7 cells using specific interaction between MUC-1 and its aptamer, covalently conjugated to the surface of GNRs by Au-thiolate chemistry and scan the signals with unique localized surface plasmon resonance (LSPR) spectra." (PMID 34277571, 2021). "MUC1 is overexpressed by many human epithelial cancers, in particular breast cancer." (PMID 34065557, 2021). "Expression of miR-497 and MUC1 was determined in breast cancer tissues and cells." (PMID 33194611, 2020).
breast carcinoma (continued). "Moreover, supernatant from MUC1-ST-induced macrophages induced the invasion through the basement membrane of the breast cancer cell line, MCF-7, in a similar manner." (PMID 33149188, 2020). "This study therefore implies that MUC1 overexpression in breast cancer in Kumasi predicts poor prognosis, with aggressive tumour types that may be highly associated with metastasis." (PMID 32377198, 2020). "Additionally, clinical research has shown that overexpression of MUC1 imparts poor prognosis in patients with breast cancer." (PMID 33194611, 2020). "Thus, up-regulated miR-497 inhibited breast cancer growth in vivo by down-regulating MUC1 expression." (PMID 33194611, 2020). "In conclusion, the present study demonstrated that overexpressing miR-497 through inhibiting methylation of its promoter region repressed proliferation and invasivity of breast cancer, and induced apoptosis in breast cancer cells through down-regulating MUC1 expression." (PMID 33194611, 2020). "MUC1 expression in various breast cancer cells showed the relevant expression patterns." (PMID 32380650, 2020). "This compound targets the MUC1 transmembrane glycoprotein, which is overexpressed in most of cancer cells, and its conjugation with MSNs has yielded excellent results targeting murine breast cancer cells expressing the human form of MUC1." (PMID 32397449, 2020). "To test this hypothesis, we investigated the role of the miR-497/MUC1 axis in breast cancer progression in vitro using MCF-7 cells." (PMID 33194611, 2020). "Moreover, our in our study we also silenced MUC1 to investigate its roles in breast cancer both in vivo and in vitro." (PMID 33194611, 2020). "Moreover, when monocytes were co-cultured with the breast cancer line T47D that carries the MUC1-ST glycoform, CXCL5 was secreted by the myeloid cells and was reduced when the T47D cells were treated with sialidase to remove the sialic acid." (PMID 33149188, 2020). "Finally, the expression of the natural form of MUC1 (using the same antibody as A) in breast cancer cells was verified by FACS." (PMID 32380650, 2020). "Our data has suggested that miR-497 negatively regulates MUC1 in breast cancer cells." (PMID 33194611, 2020). "We also observed in this study that MUC1, a key target of miR-497, was highly expressed in breast cancer cells, and that overexpression of miR-497 inhibited breast cancer cell proliferation and promoted apoptosis by down-regulating MUC1, thereby inhibiting breast cancer cell growth in vivo." (PMID 33194611, 2020). "Collectively, results of our investigation showed that restored miR-497 could serve as a tumor suppressor in breast cancer by down-regulating expression of MUC1." (PMID 33194611, 2020). "Rationale: Transformed MUC1 (tMUC1) is a cancer-associated antigen that is overexpressed in >90% of triple-negative breast cancers (TNBC), a highly metastatic and aggressive subtype of breast cancer." (PMID 32550914, 2020). "MUC1-ST-induced macrophages show further characteristics of TAMs in that they are inefficient at phagocytosis and induce the invasion of both neutrophils and the minimally invasive breast cancer cell line MCF-7." (PMID 33149188, 2020). "Expression of MUC1 was determined in breast cancer tissues using western blot analysis." (PMID 33194611, 2020). "So, we could hypothesize that the miR-497/MUC1 axis may play an important role in breast cancer progression." (PMID 33194611, 2020). "MUC1 expression in breast cancer cells was also measured using western blot analysis." (PMID 33194611, 2020). "Investigation of miR-497 and MUC1 in breast cancer cells and their functions yields a better understanding of their disease-related mechanisms and may present a promising new direction for the development of better treatments for breast cancer." (PMID 33194611, 2020). "MiR-497 was down-regulated and MUC1 was up-regulated in breast cancer tissues and cell lines." (PMID 33194611, 2020).
breast carcinoma (continued). "However, there have been a limited number of studies addressing the predictive and prognostic features of MUC1 in African breast cancer." (PMID 32377198, 2020). "Therefore, we explored the interaction between miR-497 and MUC1, aiming to identify a potential new strategy for breast cancer treatment." (PMID 33194611, 2020). "Therefore, the role of MUC1 in canine mammary tumors, particularly in regulating anti-drug resistance, is worthwhile to be investigated." (PMID 33375426, 2020). "Mucin 1 (MUC1), a transmembrane protein, is closely associated with the malignancy and metastasis of canine mammary tumors; however, the role of overexpressed MUC1 in the development of cancer cells and response to drug treatment remains unclear." (PMID 33375426, 2020). "On the other hand, high-level expression of MUC1 led to drug resistance in mammary tumors." (PMID 33375426, 2020). "Previous studies focusing on metastatic canine mammary tumors have found that MUC1 is overexpressed in both primary and metastatic sites, as well as in metastatic lymph nodes, with a statistically significant correlation between the expression level of MUC1 and distant metastasis of tumor." (PMID 33375426, 2020). "The anti-tumor activity of disulfiram was limited in CIPp cells with overexpressed MUC1, along with little interference of disulfiram on the activation of PI3K/Akt/mTOR, indicating that the level of MUC1 affected the efficiency of disulfiram in treating canine mammary tumors." (PMID 33375426, 2020). "In conclusion, our study demonstrated the importance of MUC1 in affecting the therapeutical efficiency of disulfiram against canine mammary tumors, indicating that the expression level of MUC1 should be considered for clinical use of disulfiram or other drugs targeting PI3K/Akt pathway." (PMID 33375426, 2020). "Few studies had addressed the therapeutic role of disulfiram against canine mammary tumors, here we hypothesized that the effect of disulfiram would be compromised with the high expression of MUC1." (PMID 33375426, 2020). "In addition, the role of MUC1 expressing level in affecting drug efficiency need to be validated with different kind of canine mammary tumors, and the molecular mechanism of interactions between MUC1 and PI3K/Akt/mTOR needs to be investigated as well." (PMID 33375426, 2020). "In over 90% of human breast cancer patients, overexpression of MUC1 was detected." (PMID 33375426, 2020). "Since it is known that anti-MUC1 antibodies may alter estrogen receptor activity in breast cancer, this potential interplay was investigated in OC." (PMID 30642093, 2019). "In addition, there was a correlation between IGF-1R signaling pathway and MUC1 expression in breast cancer cells." (PMID 30041514, 2019). "MUC1 is over-expressed and aberrantly glycosylated in more than 90% of breast cancer cases." (PMID 31178870, 2019). "Furthermore, a Phase III clinical trial conducted using MUC1 for treating patients with ER+ stage 2 breast cancer showed that the MUC1-vaccine-treated group displayed a significantly reduced recurrence rate (12.5%) compared to the placebo control (60%)." (PMID 31366131, 2019). "MUC1 is overexpressed on the entire cell surface in a wide variety of cancers (i.e., lung, prostate, gastrointestinal tract, etc.), especially by primary and metastatic breast cancers." (PMID 31470531, 2019). "This classification will be useful to distinguish differentially glycosylated MUC1 biologically relevant to health and disease, such as MUC1 expressed by breast cancer tissue and normal ductal epithelia, and to correlate the differential bindings to the expression profiles of glycosyltransferases." (PMID 31719620, 2019). "MUC1 is a glycoprotein that is normally expressed on glandular epithelium, but is overexpressed and under-glycosylated in most human cancers, including the majority of breast cancers." (PMID 31693710, 2019).
breast carcinoma (continued). "Our data suggest that based on its ability to detect HER2- and MUC1-positive breast cancer cells in vivo, 99mTc-HER2 and 99mTc-MUC1-targeted peptides may be promising tumor imaging probes and warrant further investigation." (PMID 31470531, 2019). "MUC1 was chosen as a model tumor antigen as it is the best characterized human tumor cell-surface antigen, which has been developed as a tumor marker for clinical use, in particular as a marker of human breast cancer." (PMID 31470531, 2019). "Similarly, sialylation of the T antigen in MUC1 on breast cancer cells creates the MUC1–ST antigen which engages Singlec-9 on tumor-associated macrophages to initiate inhibitory immune signaling through the activation of the MAPK/ERK pathway." (PMID 31157165, 2019). "Due to its characteristic aberrant glycosylation as a result of reduced activity of glycosyltransferases and accelerated activity of sialyltransferases in the MUC1 biosynthesis in breast cancer cells 12, breast-(TA)MUC1 represents a tumor-specific marker and target for therapy." (PMID 31588183, 2019). "In this study, HER2 and MUC1-based peptides were synthesized and preclinically evaluated in an effort to develop peptide-based SPECT radiopharmaceuticals derived from tumor-associated antigens for the detection of breast cancer." (PMID 31470531, 2019). "It was found that early-stage breast cancer has more frequent and higher levels of autoantibodies to glycosylated MUC1 compared to healthy controls, which indicates that autoantibodies may reflect disease progression." (PMID 30011807, 2018). "This study extends our prior work in breast cancer, which demonstrated that changes in MUC1 antigen that occur in breast cancer development could detected in vivo using TAB004 as a carrier for imaging agent." (PMID 29462213, 2018). "MUC1, which is abnormally overexpressed in most breast cancer, is physiologically expressed in PMI." (PMID 29423058, 2018). "The binding of MUC1-ST to siglec-9 on macrophages results in the expression of a tumour-associated macrophage (TAM) type phenotype, which is associated with poor prognosis in breast cancer." (PMID 29903935, 2018). "Likewise, monoclonal antibody against MUC1 increased the sensitivity of breast cancer cells to the dinuclear platinum(II) complex." (PMID 29862867, 2018). "To date, three different approaches targeting MUC1 (mAbs, vaccines and small peptide inhibitors of MUC1 cytoplasmic domain) have been developed and are in different phases of clinical trials for the treatment of human cancers, including breast cancers." (PMID 30428522, 2018). "MUC1 antibodies were found to be associated with 80% of grade III cancers as compared to 50% of early grade cancers (including grade I & II cancers), indicating their role in aggressiveness of canine mammary tumours." (PMID 30361548, 2018). "MUC1 is the target of breast cancer early diagnosis biomarkers CA27-29 and CA15-3." (PMID 28085094, 2017). "MUC1, which is part of a large family of mucin glycoproteins, is involved with cell signaling and cell-cell and cell-matrix adhesion, and may impact breast cancer recurrence via these pathways or by directly binding to and activating ERα." (PMID 29228969, 2017). "This study investigated the fabrication, characterization and application of a specific breast cancer MR imaging contrast agent, C595-mab conjugated SPIONs (SPIONs-C595) by simplified EDC method, for breast cancer detection with MUC1 over expression in early stages as an MR imaging contrast agent." (PMID 29090067, 2017). "L-BLP25 vaccine in combination with letrozole could induce an antigen-specific immune response and increase the survival advantage obviously in MUC1-expressing breast cancer mouse model." (PMID 28085094, 2017). "The rare missense mutation Q85E, identified in the MUC1 gene in the daughter of the index case with early-onset breast cancer, was absent in the mother and her affected cousin." (PMID 28241424, 2017).
breast carcinoma (continued). "Immune responses to MUC1 have been seen in breast and ovarian cancer patients and clinical studies have been initiated to evaluate the use of antibodies to MUC1 and of immunogens based on MUC1 for immunotherapy of breast cancer patients." (PMID 28245581, 2017). "VEGF165 and MUC1 are known to play key roles in breast cancer." (PMID 28841163, 2017). "Since it has been suggested that GALNT6 could regulate breast cancer cell adhesion and growth through modification of MUC1 glycosylation and stability, we therefore tested whether GALNT6 exerted its effects via MUC1 in ovarian cancer cells." (PMID 28388560, 2017). "Specifically, we sought to estimate differences in the expression of two suspected good prognosis genes (ACOX2 and MUC1) and six suspected poor prognosis genes (FAM177A1, GSTT2, PSPH, PSPHL, SQLE, and TYMS) by race, and to examine their associations with risk of breast cancer recurrence." (PMID 29228969, 2017). "Furthermore, preliminary PBMC cultures established from breast cancer patients confirm that our culture system and antigen discovery algorithm can be extended successfully to patients with MUC1- and HER2-expressing malignancies." (PMID 27974697, 2017). "HER2 and MUC1 are two well-studied antigens in breast cancer." (PMID 28085094, 2017). "Examples of other TAAs that could be used in combination with ERBB2 in targeting breast cancer include melanoma-associated antigen-A4 (MAGE-A4), mesothelin, and MUC-1." (PMID 28885562, 2017). "HuHMFG1 is an antibody against MUC1 that has been tested in clinical trials for breast cancer." (PMID 28212575, 2017). "MUC1 is overexpressed in more than 90% of breast carcinomas and we hereby report that copy number might play a significant role in this tissue, as copy gain was frequently seen in breast cancer." (PMID 28978023, 2017). "Finally, our data suggest that MUC1 represents a potential novel therapeutic target to reduce tumor growth in breast cancer." (PMID 28464016, 2017). "In normal conditions, the MUC1 gene encodes transmembrane mucin proteins, but in breast carcinomas, the MUC1 protein is not restrained to transmembrane, but rather upregulated over the cell surface with more exposed peptide epitopes due to shortened O-glycans." (PMID 27782067, 2016). "Similar to the MUC1 aptamer, the Apt-Td could preferentially bind with MUC1-positive MCF-7 breast cancer cells." (PMID 27203221, 2016). "In breast cancer, MUC1 interacts with sialoadhesin (Sn), a receptor present on the majority of infiltrating macrophages that specifically binds the sialylated form of MUC1." (PMID 27754373, 2016). "T cells from ~38% of the breast cancer patients responded to the selected MUC1 peptides." (PMID 27367740, 2016). "Moreover, Apt-Td selectively delivered Dox into the MUC1-positive breast cancer cells but reduced Dox uptake by the MUC1-negative control cells." (PMID 27203221, 2016). "Indeed, CA 15.3 measures circulating levels of fragments of MUC1/Polymorphic Epithelial Mucin, present on all breast cancer cells, whereas HER2/ECD is a part of HER2." (PMID 27709352, 2016). "Although mutation-specific vaccines are under development, there is still high interest in an off-the-shelf vaccine to a ubiquitous antigen, such as MUC1, which is aberrantly expressed on most solid and many hematological tumors, including more than 90% of breast carcinomas." (PMID 27367740, 2016). "The primary goal of this study was to evaluate whether aptamer-guided DNA tetrahedrons could selectively deliver doxorubicin to MUC1-expressing breast cancer cells." (PMID 27203221, 2016). "The Apt-Td could selectively deliver doxorubicin into the MUC1-positive breast cancer cells in vitro." (PMID 27203221, 2016). "In addition, the MUC1-C subunit forms auto-inductive interactions with the NF-κB p65 and STAT1/3 transcription factors that confer activation of the MUC1 promoter and thereby MUC1-C expression in breast cancer cells." (PMID 26930718, 2016).